TNF (tumor necrosis factor)
Diseases named in the same sentence as TNF in open-access papers (continued):
Sharing a sentence is not in itself a finding about the gene and the disease.
cancer (continued). "As a common effector of TLR4 and inflammatory cytokine receptors that promote muscle wasting including TNFα, IL-6, IL-1β and members of the TGFβ superfamily including TGFβ and activin A/myostatin, p38β MAPK plays a central role in mediating muscle wasting in murine models of cancer." (PMID 34950660, 2021). "Furthermore, the pro-inflammatory cytokines of cancer patients including TNF-α, IL-6, and IL-2R were higher than those of patients without cancer." (PMID 34277701, 2021). "Therefore, an increase in monocyte transmembrane TNF-α, with no concomitant increase in circulating TNF-α, implies a positive immune impact in T2DM patients, possibly decreasing cancer risk." (PMID 34239993, 2021). "Notably, 41% of patients treated with anti TNF-alpha never stopped their biological therapy after the diagnosis of cancer." (PMID 33540674, 2021). "Elevated TNF-α/TNFR1 and TNF-α/TNFR2 ratios indicate a decline in disease activity after 131I therapy, which is more pronounced in PTC than in PTC + AIT, suggesting that suppression of TNFR1 and TNFR2 or increased production of TNF-α is required to initiate remission of cancer." (PMID 34298820, 2021). "In our study, we could not separately evaluate the contribution TNFα, TRAF3 and GADD45A in the combination treatment-enhanced apoptosis because knockdown of either TNFα, TRAF3 or GADD45A can completely abolish the treatment-induced apoptosis and the synergy in inhibiting cancer cell growth." (PMID 34025421, 2021). "However, for selected patients with advanced cancer and severe IBD relapse, the use of anti TNF-alpha drugs could be acceptable in order to achieve a better control of symptoms and an improvement of quality of life." (PMID 33540674, 2021). "Furthermore, GO enrichment analysis shows that the cancer-related signaling pathway, the PI3K-Akt signaling pathway, the HIF1 signaling pathway, and the TNF signaling pathway may play key roles in the treatment of CRF by FSG." (PMID 33747100, 2021). "In such a follow-up study, additional inflammation parameters to CRP, such as TNF-α, IFN-γ, and/or IL-1, should be included to gain more insight into the potential mechanistic links between complement activation and pro-inflammatory processes in patients with cancer cachexia." (PMID 34830921, 2021). "Although both TNFα and its receptors’ precise role within the complex and ever-evolving TME are far from fully understood, substantial evidence has emerged that TNFα signaling has a paradoxical and dual role in cancer progression and the dynamic immunoediting process." (PMID 34445397, 2021). "In GBM cell lines U-251 and U-87, the interaction of Ras (an oncogene) with TNFα/IL-1β was found to increase hypersecretion of IL-6/IL-8 cytokines and activation of the p38 MAPK signaling pathway, leading to the creation of an inflammatory microenvironment conducive for cancer progression." (PMID 34439380, 2021). "Interestingly, TNF-α may interact with MMP-9, which involved in an invasion and migration of cancer cells." (PMID 33923108, 2021). "In particular, 96 patients exposed to vedolizumab (median time from cancer of 3.9 years, range 0.1–43) were compared to 184 and 183 patients (median time from cancer of 1.3 years, range 0–38) exposed to anti TNF-alpha or to no immunosuppressive therapy, respectively." (PMID 33540674, 2021). "Drugs inhibiting TNF are widely used for the treatment of various inflammatory and rheumatologic diseases and could be quite useful in combination with targeted therapy of NSCLC and other cancers." (PMID 33373873, 2021). "Moreover, a small set of signaling pathways (e.g., T cell receptor, B cell receptor, Fc epsilon RI, TNF) do not show important contributions to the survival of cancer patients across all four types of cancer." (PMID 33546587, 2021).
cancer (continued). "However, in human breast, ovarian and HNSCC cancers, our group and others have demonstrated the functional alteration of TA-pDC in their capacity to secrete IFN-α in response to TLR9 ligand, resulting from TGF-β1 and TNF-α produced in the TME." (PMID 33924428, 2021). "In addition, cancer cells with no NF-κB activity showed high sensitivity to TNF-α treatment and other chemotherapeutic drugs." (PMID 32784919, 2020). "Besides, in all the cancer cell lines examined in the present study, we observed that pretreatment with the MK2-specific kinase inhibitor PF-3644022 efficiently blocked the phosphorylation at S857 in response to TNF-α." (PMID 32647362, 2020). "According to the results of pathway enrichment, we believe that effects of FGHP against CHD may be due to the fact that FGHP can simultaneously target multiple pathways like pathways in cancer, HIF-1 signaling pathway, PPAR signaling pathway, TNF signaling pathway, and so on." (PMID 32508942, 2020). "In contrast, HMGB1 release from dying cancer cells can activate anticancer immunity: the complex of HMGB1 with RAGE or Toll-like receptor 4 (TLR4) triggers cascades of reaction that lead to the local secretion of proinflammatory cytokines, including IL−1, IL−6 and TNF-α." (PMID 32698492, 2020). "Cancer cell EMT could be driven by paracrine signals from the microenvironment, such as TGF-β, Wnt, Notch-1, Sonic Hedgehog (Shh), and pro-inflammatory cytokines including tumor necrosis factor alpha (TNF-α) and IL-6." (PMID 32242230, 2020). "Additionally, these junctions can be destabilized by the expressions of cytokines, chemokines, and inflammatory mediators, including VEGF, basic FGF (bFGF), TGF-ß, IL-1ß, TNF-α, interferon-γ (IFN-γ), CCL2, CXCL8, and prostaglandin-endoperoxide synthase 2 (COX2), by the cancer cells." (PMID 31900168, 2020). "Our results suggest that TNF's dual roles in either coordinating cellular responses to inflammation, or further amplifying inflammation are determined by a dynamic NFκB‐A20‐RIPK3 circuit, that could be targeted to treat inflammation and cancer." (PMID 33314666, 2020). "High plasmacytoid dendritic cells could promote the expression of CXCR4 by TNF-α/NF-κB pathway, and blocking CXCR4 could effectively inhibit cancer progression and enhanced the curative effect of immune checkpoint blockers by up-regulating Treg cells infiltration." (PMID 33324682, 2020). "However, with AIMs effects on Akt, it is hard to explain the synergistic effect between TNF-α and CDDP; TNF-α in combination with AIMs with or without CDDP exhibited a remarkable anti-cancer effect with high efficacy on reducing cell viability." (PMID 32784919, 2020). "As cancer cells frequently rely on the complementary activities of BCL-xL and MCL-1 for their survival we propose that the paracrine effects of paclitaxel, through IFN/TNF dependent NOXA induction, enhance BCL-xL dependency by decreasing the influence of MCL-1." (PMID 31937780, 2020). "In addition, biglycan, through interaction with TLR2/4 receptors on the surface of macrophages, promotes inflammation by triggering the synthesis of two cytokines important for cancer progression, TNFα and CCL2, and thus enhances tumor growth in many cancer cells." (PMID 32847060, 2020). "Other factors also are involved in the early steps of cancer cell dissemination, particularly several cytokines that are interesting therapeutic targets, for instance vascular endothelial growth factor (VEGF), tumor necrosis factor alpha and beta (TNF), and chemokine (C–C motif) ligand 2 (CCL2)." (PMID 32850309, 2020). "* Via physical contacts with cancer cells and through secreted factors, theyincreased CSC proportions, as well as EMT and migration.* The activities of the myeloid cells were mediated by or connected to solublefactors such as TNFα, IL-6 and ELR+ CXC chemokines (e.g., CXCL8 and CXCL1)." (PMID 33585241, 2020).
cancer (continued). "Since several reports have shown that TNF-α likely regulates glucose metabolism in cancer cells without HIF-1α stabilization, the TNF-α signaling pathway might be involved in the induction of aerobic glycolysis in fibroblasts." (PMID 32555715, 2020). "A recent study showed no benefit of anti-TNF-α antibodies in patients with cancer cachexia." (PMID 30754663, 2019). "This may explain why no obvious correlation between TNF-α mRNA in cancer cells and stromal miR-21 was observed." (PMID 30999696, 2019). "The stimulatory responses elicited in cancer cells by ligands of AHR like 3MC may involve a crosstalk of AHR with diverse signaling molecules and transduction pathways as EGFR, the transforming growth factor-β (TGF-β) and tumor necrosis factor-α (TNF-α)." (PMID 31370872, 2019). "Notably, these cancer biomarkers functionally comprised of several cytokines (IL-6, MIF, TGF-α, TNFα), apoptosis-related proteins (sFas, sFasL, TRAIL), growth and angiogenic factors (FGF2, HGF, SCF, VEGF), hormones (leptin, prolactin) and other biomarkers (AFP, OPN), but not carcinoma antigens." (PMID 31089160, 2019). "However, stromal fibroblastic cells located in the vicinity of TNF-α positive cancer cells did generally not show differences in the miR-21 expression patterns compared to areas without TNF-α mRNA signal." (PMID 30999696, 2019). "In particular, a cocktail mixture containing tumor necrosis factor-α (TNF-α), interleukin-1β (IL-1β), interleukin-6 (IL-6), and prostaglandin E2 (PGE2), is currently considered the gold standard for DC maturation and had been largely used in the context of anti-cancer therapeutic vaccines." (PMID 30621204, 2019). "Therefore, although the level of the TnfαmRNA expression in 4T1 tumors may not be as high as in LLC tumors as previously reported, TNFα could still be a better target to reduce the production of MCP-1 and other cancer promoting cytokines." (PMID 31888216, 2019). "Although some types of cancer cells can release certain cytokines, cachectic cancer cells do not necessarily release catabolic cytokines such as TNFα, IL-6, and IL-1β, and the vast majority of circulating cytokines are generated by immune cells in response to cancer." (PMID 31480237, 2019). "In addition, TNF-α has been found to be involved in branching morphogenesis in in vivo models, e.g., during rat mammary gland development facilitated by MMP9, suggesting that the cancer cells re-establish cellular mechanism used during early organ development." (PMID 30999696, 2019). "Moreover, Choi and colleagues reported that açaí treatment down-regulated myeloperoxidase (MPO) and proinflammatory cytokines (TNF-α, IL-1β and IL-6), inhibited cyclooxygenase 2 (COX-2), PCNA and Bcl-2, and increased Bad and cleaved caspase-3 expression in an experimental model of cancer colon." (PMID 29966007, 2018). "With the increasing application of ICPI for different cancers and the understanding of potential risks for irAE, liver function and liver biochemical tests should be closely monitored during treatment using ICPI and during treatment using anti-TNF-α agents in this patient population." (PMID 30400822, 2018). "Similarly, in many cancer cell lines, IAP proteins inhibit apoptosis induced by TNF." (PMID 29749399, 2018). "IFN-γ and TNF-α-treatment resulted in the induction of IDO and IL-6 gene expression and release in established cell lines, suggesting that the elicitation of PCa-TDSFs by these cytokines might contribute to progression of cancer into an untreatable phenotype." (PMID 29896191, 2018). "Further examination is necessary for cytokine-induced tight junction remodeling; however, TNFα might not be suitable for increasing permeability of anti-cancer drugs." (PMID 30647838, 2018). "A trial of anti-TNF-α antibodies in patients with cancer cachexia has also shown no benefit." (PMID 29338749, 2018).
cancer (continued). "The origin of cancer cachexia is multifactorial and includes reduction of food intake and abnormal energetic metabolism, driven by proinflammatory cytokines released by tumour cells, such as IFN-γ, TNF-α and nuclear factor kappa-light-chain-enhancer of activated B cells (NF-kB)." (PMID 29568412, 2018). "Blockingβ-catenin pathway significantly decreases the TNF-α-primed-conditioned medium or CCL5-mediated cancer cell progression by decreasing the enhancement of Slug, suggesting that the CCL5/β-catenin/Slug pathway plays a critical role in hMSC-mediated cancer progression." (PMID 28542126, 2017). "Concentrations of potential cancer markers (sHLA-G, IL-10 and TNF-alpha) in body fluids (serum and peritoneal fluid) are not stable, which may be associated with both their sources and natural history of the disease." (PMID 28376925, 2017). "However, the relationship between HAS3 and TNF-α expression has never been examined in human cancer patients." (PMID 28107185, 2017). "TNF-α could induce Twist1 expression and overexpression of Twist1 could promote further metastasis, which increased the expression of MMP-9, MMP-2, CD44v6 and vimentin in cancer cells." (PMID 28774312, 2017). "Importantly, innate immune stimuli (e.g. oncolytic virus (VSVΔ51-GFP), interferon γ (IFNγ), and tumour necrosis factor-like weak inducer of apoptosis (TWEAK)) synergize with LCL161 in vitro to promote TNFα signaling and reduce cell viability in Kym-1 RMS cancer cells." (PMID 27966453, 2017). "Most participants were not aware that they may need to discontinue their anti-TNF if they developed cancer." (PMID 28526972, 2017). "Overall, limiting the impact of metabolic dysregulation combined with a reduction of inflammation by targeting NF-χβ, TNF-α, the Jak/Stat pathway and the TGF-β pathway has the potential of reestablishing tissue homeostasis and turning on as a result the immune cancer kill switch." (PMID 28969664, 2017). "However, like TNF, the expression of TGF-β1 appears to be increased in cancer cells." (PMID 29228633, 2017). "Tumor necrosis-factor (TNF)-related apoptosis-inducing ligand (TRAIL) is a member of the TNF-superfamily that selectively induces apoptosis through death receptors (DRs) 4 and/or 5 in cancer cells, however, cancer cells can evade TRAIL-induced apoptosis by acquiring TRAIL-resistance." (PMID 28422730, 2017). "Moreover, CCR4 could be induced by the cytokine TNF-α in NF-κB-dependent manner and might be involved in TNF-α-induced cancer cells invasiveness." (PMID 27356745, 2016). "Identified discriminatory cancer markers include matrix metalloproteinases (i.e., MMP1, MMP3, MMP9), cytokines (i.e., interleukin-6, interleukin-8, vascular endothelial growth factor A (VEGF-A), tumor necrosis factor α (TNF-α), transferrins, and fibroblast growth factors." (PMID 27999326, 2016). "As another example, we correctly predicted that Tumor necrosis factor-α (TNF-α) and transforming growth factor-β (TGF-β) were synthetically interacting in the same pathway, as a recent study revealed that TGF-β and TNF-α act in concert to activate apoptosis in cancer." (PMID 27078000, 2016). "In addition, arrays of growth factors and chemokines secreted by stromal cells, as well as cancer cells, into the stroma, such as the nuclear factor κB, transforming growth factor β, and tumor necrosis factor α, are chemoattractants for other non-cancer cells." (PMID 27661111, 2016). "Furthermore, our findings suggest that CCR4 acts downstream of TNF-α and might play a role in TNF-α-mediated cancer cells metastasis." (PMID 27356745, 2016).
cancer (continued). "Our results clearly indicate increased levels of IL-10, TNF-α, TGF-β and VEGF both in serum and saliva and they suggest that these cytokines may constitute valuable tools in diagnosis, treatment and prognosis in cancer disease." (PMID 27547238, 2016). "Notably, TNF-α, an inflammatory pro-tumorigenic molecule, could induce the shedding of soluble B7-H3 by CRC cells, suggesting another mechanism of cancer immune evasion via B7-H3." (PMID 27626488, 2016). "Compared to DVT- cancer patients, DVT+ showed an increased fold change of 1.28 (95% CI: 1.20–1.37; p<0.0001), 1.34 (95% CI: 1.23–1.46; p<0.0001), 1.41 (95% CI: 1.30–1.54; p<0.0001), and 1.61 (95% CI: 1.45–1.78; p<0.0001) for IL-6, TNF-α, Il-1β, and VEGF, respectively." (PMID 26192925, 2015). "Since the discovery of the first tumor necrosis factor, tumor necrosis factor alpha (TNFα), members of TNF superfamily have been found, many TNF family members have shown promise in several therapeutic applications including cancer, infectious disease, transplantation and autoimmunity." (PMID 26571489, 2015). "However, LIF secretion may be stimulated by pro-inflammatory cytokines, such as IL-6, IL-1 and tumor necrosis factor (TNF)-α, leading to elevated serum LIF levels in cancer patients." (PMID 26296968, 2015). "However, when we examined the mRNA levels and supernatant content of inflammatory cytokines in hUC-MSCs and IL-6-hUC-MSCs, we found that the levels of several cancer-promoting cytokines, including CCL5, PDGF-BB, MCP-1 and TNFα, were markedly downregulated in the IL-6-hUC-MSCs." (PMID 25483835, 2015). "The first cytokine described that has an explicit impact on HSPCs is tumor necrosis factor (TNF)-like weak inducer of apoptosis (TWEAK), which is produced by monocytes, T lymphocytes and macrophages whose expression increases in contexts of acute injury, inflammatory disease and cancer." (PMID 26600740, 2015). "While the optimal DC phenotype for cancer immunotherapy remains controversial, it is increasingly recognized that incorporation of IL-12p70-producing DC1 – which subsequently polarize naïve CD4+ T-cells toward a IFN-γ and TNF-α-secreting T-helper type 1 (Th1) phenotype – appears advantageous." (PMID 26082780, 2015). "In addition, TNF-α, interferon-gamma (IFN-γ), early growth response gene-1 (EGR-1), hypoxia-inducible factor 1 alpha (HIF-1α), and transforming growth factor-beta (TGF-β) upregulate flTF in cancer cells and endothelial cells." (PMID 25084809, 2014). "However, the specific mechanisms responsible for TNF-α promoting the progression of malignant tumors have not been elucidated." (PMID 24676340, 2014). "In addition, when applied at non-toxic concentrations, some of them can sensitize cancer cells to tumor necrosis factor (TNF)-related apoptosis-inducing ligand (TRAIL) cytotoxicity." (PMID 24910845, 2014). "Furthermore, it has been suggested that MCP-1 rather than TNF-α is more important for cancer cachexia." (PMID 24963216, 2014). "Apoptotic rates of the cancer cells retrieved from the hollow fibers were measured with flow cytometric analysis, caspase 3, 8, 9 enzyme activities were detected by colorimetric assay, Fas, Fas-L, TNF-R1 and TNF-α expression were determined with elisa assay and radioimmunoassay respectively." (PMID 24684953, 2014). "We can conclude that different treatment protocols that lead to a control of TNFα levels (e.g. treatment with anti-TNF antibodies or with soluble TNF receptor) warrant consideration when designing new cancer therapies utilizing IL-12, without risking its potent antitumor activity." (PMID 24587231, 2014). "However, although TNF-α is the most potent activator of NF-κ B, elevated levels of TNF-α in tissue or serum are not very common in cancer patients." (PMID 24106481, 2013).